ALB (albumin)
Diseases named in the same sentence as ALB in open-access papers (continued):
Sharing a sentence is not in itself a finding about the gene and the disease.
tumor (continued). "In this study, combretastatin-A4 phosphate (CA4P) was utilized to reduce tumor IFP, and thereby to improve the intratumoral distribution and antitumor efficacy of nanoparticle albumin-bound paclitaxel (nab-paclitaxel)." (PMID 27531898, 2016). "To investigate if SPARC mediated the lipid deposition by chaperoning albumin-bound FA from the intravascular space to the tumor tissue, we tested the binding affinity of SPARC to albumin using pull-down assays and SPR analysis." (PMID 27776337, 2016). "The quotient of CSF/serum albumin (also called BBB ratio) is determined by the concentration of albumin in blood and CSF, which have been used extensively to mirror the BBB disruption in neuroinflammatory disease or in tumor CNS metastasis." (PMID 26586924, 2015). "Parameters which related to liver function (DBIL, ALB, PT, INR, Child-Pugh stage), inflammatory activity in the liver (ALT, AST, γ-GGT, LDH, ALP), and tumor stage (BCLC stage, AFP) were significantly different between two groups." (PMID 25688365, 2015). "In univariate analysis, predictors of OS include ECOG performance status, concurrent VI and Mets, tumor size, serum AFP, bilirubin, albumin, AST levels, reasons for discontinuation of sorafenib, and PD within 4 months." (PMID 25860213, 2015). "Multivariate Cox regression analysis indicated that serum-AFP, -CEA, -ALB, -ALP, tumor size, tumor number, TNM, and MRP8 ratio were independent prognostic factors for OS in ICC patients after the surgical resection." (PMID 26472105, 2015). "Univariate analysis showed that ECOG score, Child-Pugh classification, albumin, hemoglobin, mean BED, and mean RT duration were statistically significant predictors of tumor response." (PMID 26072055, 2015). "After multivariate Cox regression analysis of these variables using AIC as a stopping rule, we identified eight risk factors as independent predictors for OS in HCC: tumor size, tumor capsule, pathological grades, TBIL, ALB, PT, AFP, and tumor number." (PMID 25776856, 2015). "Univariate analysis showed that the OS of all 99 patients was also significantly influenced by age, ECOG performance status, tumor size, platelet count, AST level, AURKA expression level, and treatment response in addition to albumin and sodium levels." (PMID 24901229, 2014). "In this study, human serum albumin (HSA) conjugates of SN38 were formulated to overcome the solubility problem beside improving the active form stability and tumor tissue targeting." (PMID 24895635, 2014). "Throughout tumor sections from mice treated with PBS and IgG control, we found albumin within the perivascular space." (PMID 25238146, 2014). "In the current study, we developed novel tumour-targeting nanospheres (FA-NIR 797-MAN), composed of NIR 797 isothiocyanate-folate-SPIONs-albumin nanospheres." (PMID 25188308, 2014). "This was because of increase in convective velocity heterogeneity resulting from very high reduction in the tumor IFP, which directed the interstitial fluid and albumin tracer away from the tumor into adjacent normal tissue." (PMID 24619021, 2014). "Interestingly, albumin has been shown to be efficiently taken up by phagocytes of sentinel lymph nodes in mice, and when conjugated as a vaccine it resulted in increased accumulation in the lymph node followed by enhanced T-cell priming and anti-tumor efficacy." (PMID 25674083, 2014). "Several previous studies on prognostic factors in NBNC-HCC patients identified gender, serum albumin level, DCP, tumor size, tumor capsule, and tumor differentiation as significant independent factors for OS." (PMID 24745029, 2014). "Tumor angiograms were obtained from the early dynamic enhanced images, acquired within six minutes after the administration of albumin-Gd-DTPA, when the leakage of the MMCA to the tumor interstitium was minimal." (PMID 24466160, 2014).
tumor (continued). "Moreover, it is hypothesized that the albumin-bound Nab-paclitaxel may selectively accumulate in the pancreatic stroma via its binding to secreted protein acidic and rich in cysteine (SPARC) matricellular glycoprotein which binds albumin and is overexpressed in tumor stroma." (PMID 24782785, 2014). "Then, we looked at the association between survival and clinical parameters including age, etiology, the largest size of tumor, the number of lesions, serum markers such as bilirubin, creatinine, INR, CRP, albumin, and AFP." (PMID 24367506, 2013). "Multivariate regression analyses were performed to identify which of the following factors were the predictors of the hypermethylation group: serum albumin, AFP, and tumor multiplicity." (PMID 23678400, 2013). "Further experiments demonstrated that DBHB bound strongly to albumin, possibly explaining the treatment failure of DBHB delivered through the i.v. route in an in vivo tumor model." (PMID 23519198, 2013). "Studies have demonstrated that the α-fetoprotein (AFP), carcinoembryonic antigen (CEA), ubiquitin C (UbC), murine albumin (mAlb), prostate-specific antigen (PSA) and the glucose transporter gene 1 (GTI-1.3) promoters all lead to tumor-specific hNIS expression." (PMID 23420532, 2013). "Subsequently, for minimize the confounding factors, propensity score analysis with one-to-one nearest neighbor matching method was applied, including age, gender, tumor size and number, serum bilirubin, ALT, albumin, and AFP." (PMID 23874536, 2013). "Furthermore, it has been postulated that the permeability of blood vessels surrounding brain metastases is also increased, which may explain the widespread albumin immunoreactivity evident 9 days following CRCTU tumour injection into the internal carotid artery." (PMID 23374226, 2013). "Tumour incidence and volume, plus immunoreactivity to albumin, IBA1 and GFAP, were used as indicators of tumorigenicity and tumour interaction with the host brain microenvironment." (PMID 23374226, 2013). "Univariate analysis revealed that microvascular invasion, tumor number >1, macrovascular invasion, ascites, AFP>25 ng/mL, albumin ≤ 4.0 g/dL, and furin expression T/N ratio <3.5 were significantly associated with a shorter DFS." (PMID 22808247, 2012). "Recently, a TIMP-2 fusion protein with human serum albumin (HSA/TIMP-2) was produced with high yield from the yeast Saccharomyces cerevisiae and demonstrated an inhibitory effect against tumor growth." (PMID 22545131, 2012). "By multivariate analysis male, AST > 34IU/L, albumin ≦ 3.5 g/dl, AFP > 15 ng/dl, tumor size > 5 cm in diameter were independent factors contributing to tumor recurrence within 5 years." (PMID 21269525, 2011). "The male-to-female odds ratio is 2.079, AST > 34 to AST ≦ 34 is 1.704, ALB ≦ 3.5 to ALB > 3.5 is 3.436, AFP > 15 to AFP ≦ 15 is 1.726, and tumor > 5 cm to ≦ 5 cm is 1.793." (PMID 21269525, 2011). "For other tumour types, more elaborate and sophisticated scores have been published, which integrate other parameters such as lymphocyte count, LDH level or albumin." (PMID 21505457, 2011). "The Wald tests showed that all 5 explanatory variables gender, AST, ALB, AFP, and tumor size contributed significantly to the model." (PMID 21269525, 2011). "The extracellular volume (ECV) and plasma volume (PV) of tumor and skin were determined by the dilution of 51Cr-EDTA and 125I-labeled serum albumin, respectively." (PMID 19997591, 2009). "These included infiltrative tumour, liver replacement by tumour ≥ 70%, elevation in liver enzymes (ALT/AST) ≥ 5 x ULN, a combination of tumour volume ≥ 50% and albumin < 3 g/dL, bilirubin elevation ≥ 2 mg/dL." (PMID 21614250, 2006). "The extended circulation time also augments passive tumor accumulation through the enhanced permeability and retention (EPR) effect, where the leaky vasculature and poor lymphatic drainage of tumors allow albumin to preferentially extravasate and persist within tumor tissues." (PMID 41489768, 2026).
tumor (continued). "The interaction of albumin with receptors that are overexpressed in TNBC tissues, such as gp60 and SPARC, allows for active targeting and transcytosis of drug-loaded nanoplatforms to tumor locations." (PMID 41489768, 2026). "In fact, in the multivariable analysis, the albumin level and tumor extension were independent prognostic factors, rather than resectability." (PMID 41504962, 2026). "Systemic inflammatory and immunonutritional biomarkers, including the hemoglobin-albumin-lymphocyte-platelet (HALP) score, systemic immune-inflammation index (SII), and lymphocyte-to-monocyte ratio (LMR), may reflect host-tumor interactions." (PMID 42137152, 2026). "Specifically, these conjugates exhibited a tumor-to-kidney ratio that was 5 to 6 times higher than those without the albumin binder, which resulted in extended survival." (PMID 41590529, 2026). "It was observed that low HALP levels, low albumin values and high LCR levels were independent risk factors for early recurrence and short survival, regardless of gender, tumor stage and other variables." (PMID 40282930, 2025). "This is consistent with findings that weaker albumin binders or suboptimal linker design can shorten blood half-life while still maintaining enhanced tumor accumulation relative to non-binder analogs." (PMID 40724817, 2025). "We also established that liver function markers (ALT, AST, GGT, ALB, and TBIL) could reflect hepatocyte integrity, biliary excretion, and synthetic function, potentially influencing tumor invasiveness and prognosis." (PMID 41237121, 2025). "To explore this mechanism, we selected PV-1, a tumor endothelial cell-specific marker, along with Caveolin-1, which is known to facilitate albumin endocytosis by endothelial cells, and SPARC, a protein that specifically binds to albumin." (PMID 40429837, 2025). "The control and non-tumor treatment groups (Control/GSO, Control/GSONE) clustered together, characterized by elevated antioxidant enzyme activities (SOD, CAT, GSHP-x, GSH), albumin (ALB), and total protein (TP), alongside lower levels of pro-apoptotic and oxidative stress markers." (PMID 41228521, 2025). "For example, genetic variation observed in albumin levels can affect how a BAA patient metabolizes an ICI, while social determinants of health, such as access to healthcare and socioeconomic status, can impact tumor sizes at the time and age of diagnosis." (PMID 39941550, 2025). "Nonetheless, Performance Status (PS) score, Patient-Generated Subjective Global Assessment (PG-SGA) score, tumor stage, prealbumin, albumin, and body fat percentage were not identified as independent factors influencing elevated ECW/TBW." (PMID 40842552, 2025). "We identified six signature LRGs (ALB, G6PD, HMGA1, MKI67, RACGAP1, and RFC4) possess prognostic potential, correlation with immune infiltration, and lactylation-related pathways, providing novel insights into tumor microenvironment (TME) of HCC." (PMID 40421085, 2025). "Weight increased to 41 kg, albumin 34 g/L, prealbumin 0.18 g/L, total lymphocyte count 2.1 × 109/L. Repeat chest CT showed no significant tumor progression, and quality of life improved significantly." (PMID 41398835, 2025). "In MSBO, prolonged tumor burden and impaired oral intake frequently lead to negative nitrogen balance—where protein catabolism exceeds synthesis—resulting in reduced albumin concentrations." (PMID 41398263, 2025). "In CA-IX-targeted In-111 tracers bearing albumin binders, early-time biodistribution data show increased blood and tumor activity and reduced kidney uptake compared with non-binder versions." (PMID 40724817, 2025). "We hypothesized that markers of liver functional reserve and systemic inflammation, such as albumin levels and CRP/albumin ratio, would outperform classical tumor markers for early mortality prediction in this specific patient population." (PMID 41590616, 2025).
tumor (continued). "Patients with low AFR tended to have poorer liver function (high AST, GGT, and TBIL levels, high Child-Pugh scores, and low albumin levels), evaluated tumor marker levels (CEA, CA199, and CA125) and worse tumor conditions (larger tumor volume, poor tumor differentiation, and liver capsule invasion)." (PMID 41256327, 2025). "In terms of resectable PDAC categorization, the tumor size represented the anatomical classification, CA19-9 and DUPAN-2 levels represented the biological classification, and the albumin level and neutrophil-to-lymphocyte ratio represented the conditional classification." (PMID 39847284, 2025). "Based on the glutamate–urea–lysine (GUL) structure, Lu-177 Ludotadipep is designed to extend the circulation time by binding to albumin, reducing non-specific organ uptake, increasing total tumor absorption, and lowering the side effects with smaller doses." (PMID 40426959, 2025). "Therefore, it is advantageous to have serum albumin first binding as a carrier to enhance drug-delivery then ultimately reach its target, the MAOA-expressing tumor." (PMID 39904854, 2025). "Additionally, the albumin-bilirubin (ALBI) grade, a recently proposed biomarker for assessing liver reserve before surgery, has emerged as a potential surrogate predictor of tumor recurrence after resection." (PMID 40934000, 2025). "The present study adds to our previous characterizationof heterobivalent(SST2/albumin) radioligands, named NODAGA-cLAB-TATEs, with the primary aim of identifying the mechanistic basis for theincreased integral tumor uptake of [64Cu]­Cu-NODAGA-cLAB4-TATE compared to [64Cu]­Cu-NODAGA-TATE." (PMID 40393943, 2025). "The albumin-targeted Pt-MSA-2 drug significantly inhibited tumor growth after intravenous application, while the non-maleimide complex was effective only when applied peritumorally." (PMID 40191696, 2025). "When these albumin nanoparticles are formed, binding sites on albumin are unmasked that bind clinically relevant, therapeutic antibodies that allow drug targeting of the NIC to the tumor microenvironment." (PMID 40244130, 2025). "The single HCC case that was negative on albumin ISH was a poorly differentiated tumor with suboptimal mRNA preservation related to prior radiofrequency ablation." (PMID 40941632, 2025). "Further interventional studies should be conducted to investigate whether intervening with serum albumin levels and adjusting NPAR levels in tumor patients with high levels of inflammation can improve the care and overall well-being of cancer survivors." (PMID 40313883, 2025). "The findings revealed that Blautia wexlerae exhibits a significant positive correlation with total protein and albumin, whereas Fusicatenibacter_saccharivorans displays a negative correlation with tumour size." (PMID 40852466, 2025). "The predominance of albumin and CRP/albumin ratio over conventional tumor markers underscores that, in this specific population, host factors may be more decisive than tumor burden itself in shaping short-term prognosis." (PMID 41590616, 2025). "Tumor markers significantly declined post-operatively (CA125 191 U/mL, HE4 145 pmol/L), while proteinuria persisted (3+), and serum albumin decreased to 16 g/L but increased to 25.9 g/L after albumin infusions." (PMID 41244787, 2025). "In patients undergoing repeated tumor resection, BMI and serum albumin exhibited no significant change over time (all p > 0.05)." (PMID 39841283, 2025). "Abraxane®'s mechanism of action also involves albumin's natural interaction with specific receptors, such as gp60 and SPARC (secreted protein acidic and rich in cysteine), which are overexpressed in many tumor cells." (PMID 40343307, 2025). "The highest tumor uptake of PSMA-NARI-56 (40.56 ± 10.01%ID/g) was observed after 48 h, and the tumor uptake of PSMA-NARI-56 was also 2.4-fold higher than that of PSMA-617 after 72 h, which confirms the effect of higher plasma protein (albumin) binding on PSMA-expressing tissue uptake." (PMID 40806707, 2025).
tumor (continued). "NRI integrates parameters of albumin and body weight, while SIRI integrates parameters of three inflammatory cells (lymphocytes, neutrophils, and monocytes), both of which have been proven to be effective prognostic indicators in various tumor models." (PMID 39304598, 2025). "To this end, we coupled peptide 5a to human serum albumin (HSA), to increase the peptide plasma half-life and tested its ability to block TGFβ activation in various in vitro and in vivo tumor models and induce anti-tumor effects." (PMID 40055773, 2025). "Studies have also shown that by exploiting the tumor’s preference for albumin uptake and the enhanced permeability and retention (EPR) effect, albumin bio-mineralized nanoparticles can be preferentially delivered to the tumor site and thus serve as an excellent photothermal therapeutic medium." (PMID 41438076, 2025). "Significant differences were found between groups in tumor diameter, neutrophil and lymphocyte counts, T-stage, N-stage, CA 15 − 3, CEA, albumin, alkaline phosphatase, neutrophil-to-lymphocyte ratio, and the systemic immune inflammation index (SII) (all p < 0.05)." (PMID 41398653, 2025). "The persistently high tumor uptake of PSMA-NARI-56 is attributed to slower blood clearance and enhanced interactions with albumin, which reduce the steric accessibility of PSMA ligands by metabolizing enzymes, and thus may have higher metabolic stability." (PMID 40806707, 2025). "CRP, albumin and most composite inflammation scores, but not dNLR, remained as independent prognostic factors for OS after adjusting for age, CgA, PS, Ki‐67, tumour site and number of previous treatments." (PMID 38477040, 2025). "Age, BMI, HGB, Serum ALB, Serum CEA, CONUT score, tumor size, pT stage, pN stage, nerve invasion, vascular invasion, tumor differentiation, and postoperative chemotherapy were the factors that influenced the prognosis of GC, according to the Cox's univariate analysis (P < 0.05 for all)." (PMID 40097940, 2025). "The univariate analysis shows that patient age, CEA level, lymphocyte count, albumin, NLR, SII, PNI, tumor distance from the anus, tumor size, tumor invasion of the intestinal wall, cT stage, cN stage, TRG grade, KRAS status, and microsatellite status are associated with survival." (PMID 40444087, 2025). "The presence of micrometastatic tumor cells in the liver may also activate Kupffer cells to produce a variety of cytokines (IL-1b, IL-6, TNF), which regulate albumin synthesis by hepatocytes." (PMID 40004975, 2025). "In the univariate analyses, several risk factors were identified: age, sex, BMI, ASA score, EBL > 30 mL, preoperative C-reactive protein, preoperative albumin, tumor size, T stage, and lack of duodenal stump reinforcement." (PMID 40507217, 2025). "This study found that common biomarkers, such as tumor size, AST, and albumin after conversion therapy, were not independently associated with recurrence, suggesting that the mechanisms of postoperative recurrence are complex." (PMID 40934000, 2025). "Nanoparticle albumin-bound paclitaxel (nab-PTX) accounts for a major advancement in PC treatment by enhancing drug delivery and tumor penetration while diminishing treatment-emergent adverse events (TEAEs) and toxicities correlated with conventional paclitaxel." (PMID 40427222, 2025). "Before matching, patients in the CIRT group were significantly older than those in the LR group, but the groups did not significantly differ in terms of sex, tumor size, Child–Pugh class, albumin‐bilirubin (ALBI) grade, or etiology." (PMID 40995609, 2025). "In this study, we investigated the relationships between various factors, including age, tumor history, hemoglobin, red blood cell count, preoperative blood pressure, duration of surgery, APTT, D-dimer, total protein, albumin, and calcium, and the likelihood of developing DVT after laparoscopy." (PMID 40520687, 2025).